CRELD1 (CRELD disulfide isomerase 1)
Description:
Protein disulfide isomerase (By similarity). Promotes the localization of acetylcholine receptors (AChRs) to the plasma membrane (By similarity).
Synonyms: CIRRIN; AVSD2; JELANS
Tractability: Antibody: UniProt predicts a signal peptide or a membrane-spanning region. PROTAC: ubiquitination databases record sites on it; its protein half-life has been measured.
Gene: Protein-coding gene on chromosome 3 (9,933,793 to 9,945,413, forward strand). Ensembl gene ENSG00000163703.
Subcellular location: Membrane
Subcellular location (Human Protein Atlas): Cytosol; Nucleoli
Gene Ontology:
Molecular function: protein binding; extracellular matrix structural constituent; protein disulfide isomerase activity; calcium ion binding
Biological process: cardiac septum development; endocardial cushion development
Cellular component: extracellular matrix; non-collagenous component of basement membrane; glutamatergic synapse; membrane; synapse
Genetic constraint (gnomAD): Loss-of-function variants: 41 observed, 60.14 expected, observed/expected ratio (o/e) 0.68, 90% interval 0.53 to 0.88. The upper end of that interval is the gene's LOEUF score, 0.88, which puts it in group 3 of 6, group 1 being the genes least tolerant of losing a copy. Missense variants: 497 observed, 559.8 expected, observed/expected ratio (o/e) 0.89, 90% interval 0.82 to 0.96. Synonymous variants: 219 observed, 210.1 expected, observed/expected ratio (o/e) 1.04, 90% interval 0.93 to 1.17.
Gene-disease validity (ClinGen):
ClinGen rates the evidence that CRELD1 causes each of these diseases.
congenital heart disease (autosomal dominant): Limited. A heart disease that is present at birth.
Homologues: Orthologues: chimpanzee CRELD1 (99% identical), dog CRELD1 (94% identical), pig CRELD1 (94% identical), guinea pig CRELD1 (92% identical), mouse Creld1 (91% identical), rat Creld1 (91% identical), macaque CRELD1 (83% identical), rabbit CRELD1 (67% identical), tropical clawed frog creld1 (57% identical), zebrafish creld1b (56% identical), zebrafish creld1a (23% identical), Caenorhabditis elegans ZK1193.2 (18% identical), and 7 more. Paralogues in human: CRELD2 (41% identical), CD93 (24% identical), FBLN7 (19% identical), DLL3 (18% identical), CD248 (17% identical), DLK2 (15% identical), WIF1 (14% identical), CLEC14A (12% identical).
Diseases named in the same sentence as CRELD1 in open-access papers:
CRELD1 is named in the same sentence as 31 diseases in open-access papers, as found by Europe PMC text mining. Sharing a sentence is not in itself a finding about the gene and the disease. The quoted sentences say what the papers report.
atrioventricular septal defects (7 papers, 2010 to 2025). "UniProt review of candidate genes demonstrated that CRELD1 is associated with atrioventricular septal defects." (PMID 36929416, 2023). "Several mutations of CRELD1 have been reported to contribute to occurrence of cardiac atrioventricular septal defects in Down syndrome." (PMID 28591652, 2017). "It has been reported that missense mutations in the CRELD1 gene increases an individual's susceptibility to atrioventricular septal defects, but the physiological roles of these family members remain poorly understood." (PMID 21106106, 2010). "Mutations in CRELD1, the human ortholog of CRLD-1A, are linked to atrioventricular septal defects, which represent more than 7% of all congenital heart defects in human." (PMID 30407909, 2018). "Missense mutations in human CRELD1 are linked to atrioventricular septal defects (AVSD) and in mice Creld1-/- embryos die at embryonic day 11.5 with several defects including heart development defects." (PMID 30407909, 2018). "CRELD1, which was the top-scoring gene in VAAST 2.0 and highly ranked in all 3 gene burden tests, has been implicated in both syndromic and non-syndromic CHD, specifically atrioventricular septal defects." (PMID 36929416, 2023). "For example, in the case of atrial septal defect (ASD) and ventricular septal defect (VSD), candidate genes can be counted: NKX2-5, GATA4, TBX20, MYH6, and TBX5, while the pathogenesis of atrioventricular septal defect (AVSD) involves genes, such as PTPN11, KRAS, SOS1, RAF1, and CRELD1." (PMID 34946970, 2021).
Down syndrome (6 papers, 2014 to 2025). "We confirmed the status of CRELD1 mutations as modifiers for heart defects using a mouse model, where loss-of-function for CRELD1 was shown to increase cardiac septal defects when expressed on a Down syndrome mouse model background." (PMID 25328912, 2014). "The variant rs73118372(c.1136 T > C) in Exon 9 of CRELD1 is associated with Downs syndrome." (PMID 37322441, 2023). "Importantly, we have shown that inactivating mutations in Creld1 confer significant risk for the development of cardiac septal defects when crossed with the highly susceptible TS65Dn mouse model for Down syndrome." (PMID 25328912, 2014). "This has been demonstrated for the AVSD2 gene (MIM 607170), CRELD1, where missense mutations occur in both simplex AVSD and Down syndrome-associated AVSD." (PMID 25328912, 2014). "In a cohort of patients with Down syndrome and AVSD, variants with the highest probability of being damaging in cases compared to Down syndrome patients without cardiac defects were in the VEGF-A pathway genes COL6A1, COL6A2, CRELD1, FBLN2, FRZB, and GATA5." (PMID 31888141, 2019).
diabetes (3 papers, 2023 to 2024). "All except CRELD1 and ENPP7 have previously been directly or indirectly associated with T2DM, as well as other diabetes types." (PMID 37590326, 2023). "In addition, we identify several proteins biomarkers to be associated with glycaemic deterioration in diabetes, including NogoR (RTN4), IL-18Ra, CRELD1, ENPP7 and FAS." (PMID 37137910, 2023). "This technology has led to the discovery of novel biomarkers such as Growth differentiation factor-15/Macrophage inhibitory cytokine-1 (GDF15/MIC-1), interleukin (IL)-18Ra, and Cysteine rich with EGF like domains 1 (CRELD1), which are indicative of disease progression in diabetes." (PMID 39033121, 2024).
epilepsy (3 papers, 2025). A brain disorder characterized by episodes of abnormally increased neuronal discharge resulting in transient episodes of sensory or motor neurological dysfunction, or psychic dysfunction. "In conclusion, the CRELD1 gene can be considered as a candidate for undiagnosed neurodevelopmental disorders, especially when associated with arthrogryposis and epilepsy." (PMID 40980404, 2025). "CRELD1 is a known heart disease gene, yet it has recently been implicated in a range of neurodevelopmental disorders, including epilepsy and movement disorders, for which the cerebellar hemisphere is a major player." (PMID 41345545, 2025). "This work identified a CRELD1 compound heterozygous pathogenic variant as responsible for a rare disease characterized by arthrogryposis, muscle weakness, severe global developmental delay and epilepsy." (PMID 40980404, 2025). "More recently, biallelic CRELD1 variants have been implicated as the cause of a syndromic autosomal recessive neurodevelopmental disorder featuring early-onset epilepsy, hypotonia, global developmental delay, and variably associated craniofacial and cardiac features." (PMID 40870020, 2025). "Hence, our study identifies compound heterozygous CRELD1 variants responsible for a rare neurodevelopmental disorder characterized by arthrogryposis, muscle weakness and epilepsy." (PMID 40980404, 2025). "Patients 1 and 2 exhibit profound hypotonia, developmental delay, feeding difficulties, early-onset epilepsy, and microcephaly, along with dysmorphic craniofacial features, including cleft palate and flat midface, a manifestation that further supports the role of CRELD1 in craniofacial development." (PMID 40870020, 2025).
developmental delay (2 papers, 2025). "Biallelic disease causing variants (DCVs) in CRELD1 have recently been recognised as the cause of a neurodevelopmental disorder that typically presents with early-onset epilepsy, hypotonia, feeding difficulties, and developmental delay, often accompanied by craniofacial and cardiac anomalies." (PMID 40870020, 2025).
Bradycardia (1 paper, 2025). A slower than normal heart rate (in adults, slower than 60 beats per minute). "Although congenital heart defects are variably reported in patients with biallelic CRELD1 variants, conduction abnormalities such as bradycardia and prolonged PR intervals have been observed more frequently than structural anomalies." (PMID 40870020, 2025).
cardiac septal defects (1 paper, 2014). "Reduced expression of CRELD1 resulted in a significant increase in cardiac septal defects in the offspring demonstrating that loss-of-function for CRELD1 is a genetic modifier for CHD." (PMID 25328912, 2014).
ciliopathy (1 paper, 2023). A genetic disorder of the cellular cilia or the cilia anchoring structures, the basal bodies, or of ciliary function. "ADAMTS18 and CRELD1 were both linked to heterotaxy/ciliopathy." (PMID 36929416, 2023).
congenital myasthenic syndrome (1 paper, 2018). Congenital myasthenic syndrome (CMS) is a group of genetic disorders of impaired neuromuscular transmission at the motor endplate characterized by fatigable muscle weakness. "Hence, CRELD1 potentially represents a novel target to modulate AChR levels in pathological contexts such as congenital myasthenic syndromes and possibly chronic exposure to nicotine, which causes increased AChR expression in the brain of cigarette smokers." (PMID 30407909, 2018).
glioblastoma (1 paper, 2020). The most malignant astrocytic tumor (WHO grade IV). "Among genes whose high expression correlates with decreased survival in glioblastoma, we identified several components of the “matrisome” and associated factors (FAM20C, SEMA3F, ADAMTSL4, ADAMTS14, SERPINA5, and CRELD1)." (PMID 32488114, 2020).
glioma (1 paper, 2024). A benign or malignant brain and spinal cord tumor that arises from glial cells (astrocytes, oligodendrocytes, ependymal cells). "While mutations in EFEMP2, ADAM10, SERPINH1, ADAM15, GAS6 and TNXB were detected only in patients with glioma grade 3, mutations in LTBP2, DCN, CRELD1 and HAPLN3 were observed only in patients with glioma grade 4, GBM." (PMID 38272115, 2024).
Loeys-Dietz syndrome (1 paper, 2023). Loeys-Dietz syndrome is a rare genetic connective tissue disorder characterized by a broad spectrum of craniofacial, vascular and skeletal manifestations with four genetic subtypes described forming a clinical continuum. "As BAV is also enriched in other genetic syndromes, such as Loeys-Dietz syndrome, validation could include a similar study investigating rare CRELD1 variation in similarly sensitized BAV populations that have animal models available for later functional validation." (PMID 36929416, 2023).
neurodevelopmental disorder (3 papers, 2025). A behavioral and cognitive disorder with onset during the developmental period that involves impaired or aberrant development of intellectual, motor, or social functions. "Our findings contribute to the expanding understanding of CRELD1-associated neurodevelopmental disorder, reinforce genotype–phenotype correlations, and support a broader, more nuanced view of the clinical manifestations of this rare disorder." (PMID 40870020, 2025). "These variants support a strong genotype–phenotype correlation and affirm the pathogenicity of this allele combination in the context of CRELD1-related neurodevelopmental disorders." (PMID 40870020, 2025). "Variant modelling in C. elegans causes reduced acetylcholine receptor levels at the neuromuscular junction, demonstrating variant pathogenicity and establishing CRELD1 mutations as causative of this neurodevelopmental disorder." (PMID 40980404, 2025). "More recently, biallelic CRELD1 variants have been associated with syndromic and non-syndromic neurodevelopmental disorders (NDDs)." (PMID 40870020, 2025).
CRELD1 also shares sentences with these, for which no sentence is quoted: heart disease (2 papers); arthrogryposis (1); atrial septal defect (1); congenital heart disease (1); early-onset epilepsy (1); Fever (1); focal epilepsy (1); heart defects (1); Hurler syndrome (1); infantile epilepsy (1); infection (1); microcephaly (1); movement disorder (1); pheochromocytoma (1); retinal angiomas (1); thrombosis (1); Turner syndrome (1); ventricular septal defect (1).